CA9 (carbonic anhydrase 9)
Description:
Catalyzes the interconversion between carbon dioxide and water and the dissociated ions of carbonic acid (i.e. bicarbonate and hydrogen ions).
Synonyms: CAIX; MN
Tractability: Small molecule: an approved drug acts on it; a structure with a bound ligand is known; a high-quality ligand is known; it has a binding pocket of medium quality; it belongs to a druggable protein family. Antibody: a drug acting on it is in phase 2 or 3 trials; UniProt places it where antibodies can reach, with high confidence; its Gene Ontology location is reachable by antibodies, with high confidence; UniProt predicts a signal peptide or a membrane-spanning region; the Human Protein Atlas places it where antibodies can reach. PROTAC: a small molecule that binds it is known.
Target class: Enzyme; Lyase
Chemical probes: PD081985, PD134189, PD134190
Gene: Protein-coding gene on chromosome 9 (35,673,928 to 35,681,159, forward strand). Ensembl gene ENSG00000107159.
Subcellular location: Nucleus; Nucleus, nucleolus; Cell membrane; Cell projection, microvillus membrane
Subcellular location (Human Protein Atlas): Plasma membrane
Pathways (Reactome):
Cellular responses to stimuli: Regulation of gene expression by Hypoxia-inducible Factor
Metabolism: Reversible hydration of carbon dioxide
Gene Ontology:
Molecular function: carbonate dehydratase activity; molecular function activator activity; protein binding; zinc ion binding
Biological process: response to hypoxia; response to testosterone; response to xenobiotic stimulus
Cellular component: plasma membrane; membrane; basolateral plasma membrane; microvillus membrane; nucleolus; nucleus
Genetic constraint (gnomAD): Loss-of-function variants: 44 observed, 55.38 expected, observed/expected ratio (o/e) 0.79, 90% interval 0.62 to 1.02. The upper end of that interval is the gene's LOEUF score, 1.02, which puts it in group 4 of 6, group 1 being the genes least tolerant of losing a copy. Missense variants: 574 observed, 607.77 expected, observed/expected ratio (o/e) 0.94, 90% interval 0.88 to 1.01. Synonymous variants: 253 observed, 255.02 expected, observed/expected ratio (o/e) 0.99, 90% interval 0.89 to 1.1.
Homologues: Orthologues: chimpanzee CA9 (98% identical), macaque CA9 (92% identical), dog CA9 (82% identical), pig CA9 (79% identical), rabbit CA9 (78% identical), guinea pig CA9 (72% identical), rat Car9 (71% identical), mouse Car9 (70% identical), tropical clawed frog ca9 (34% identical), Caenorhabditis elegans cah-5 (20% identical), zebrafish ca2 (20% identical), zebrafish cahz (20% identical), and 13 more. Paralogues in human: CA14 (28% identical), CA12 (27% identical), CA6 (25% identical), CA7 (20% identical), CA4 (20% identical), CA13 (19% identical), CA8 (19% identical), CA2 (19% identical), CA5A (18% identical), CA5B (18% identical), CA1 (18% identical), CA3 (18% identical), and 2 more.
Diseases named in the same sentence as CA9 in open-access papers:
CA9 is named in the same sentence as 294 diseases in open-access papers, as found by Europe PMC text mining. Sharing a sentence is not in itself a finding about the gene and the disease. The quoted sentences say what the papers report.
breast carcinoma (245 papers, 2003 to 2026). "Accumulating evidence indicates that CA9 expression is suggestively linked with poor clinical outcomes across various malignancies, including renal cell carcinoma, head and neck cancer, breast cancer, and gastric cancer." (PMID 41357200, 2025). "CA9 is highly expressed in hypoxic CAFs and to a lesser extent in tumor cells and is associated with higher recurrence and poor survival rates in breast cancer patients." (PMID 35884382, 2022). "It was reported that CA9 was associated with the migration and invasion of breast cancer cells and cervical cancer cells." (PMID 36467089, 2022). "Because TNBC patients are usually the basal subtype, CA9 mRNA expression in the basal breast cancer patients predicts reduced survival." (PMID 29965974, 2018). "Several previous reports have already associated breast cancer outcomes with levels of HIF-1 alpha or CA9 proteins." (PMID 28430808, 2017). "Since CA9 was recently reported to play an important role in breast cancer stem cell survival, we investigated the association of BMI1 with CA9 in esophageal cancer." (PMID 26156831, 2015). "In breast cancer, abundant expression of CA9 and GLUT-1 was shown to be associated with high-grade cancers and poor prognosis." (PMID 25128202, 2014). "CA9 encodes carbonic anhydrase IX, an endogenous marker of hypoxic cells in breast cancers." (PMID 30279964, 2018). "Concerning the specific cancer that is associated with the existence of CA9, the expression of CA9 was more common in prostate cancer than in nodular prostate hyperplasia, and the higher expression of CA9 was correlated to poor survival in certain types of breast cancers." (PMID 32365566, 2020). "We assessed upregulation of hypoxia-induced CA9 in each breast cancer cell line cultured in normoxia or hypoxia for 8–48 h." (PMID 39838295, 2025). "To shed more light on the prognostic significance of CA IX in BC, we examined CA9 gene expression according to various clinicopathological characteristics using the Breast Cancer Gene-Expression Miner." (PMID 36901756, 2023). "Consistent with our findings from Basal-like breast cancer, previous literature emphasizes, in particular, that CA9 negatively predicts survival." (PMID 37098526, 2023). "Previous studies confirmed that CA9 and hsa-miR-34a interacted with each other to regulate breast cancer stem cells." (PMID 36313765, 2022). "Carbonic anhydrase 9 (CA9) was reported to be associated with chemosensitivity and prognosis in breast cancer patients treated with taxane and anthracycline." (PMID 35911770, 2022). "The CA9 inhibition-induced apoptosis by other agents has also been described in colorectal, cervical and breast cancer." (PMID 36672576, 2022). "Ectopic expression of CA9 is a biomarker of poor prognosis in breast cancer, tongue squamous cell carcinoma, and pancreatic and lung cancers." (PMID 35626004, 2022). "We show that HIF stabilization and expression of a key HIF target, CA9 are similarly induced in response to hypoxia in both breast cancer subtypes." (PMID 36077517, 2022). "In the six human breast cancer cell lines with different molecular subtypes, the influence of hypoxia (0.1% O2) on CA 9/CA IX and CA 12/CA XII mRNA and protein expression levels was investigated." (PMID 34445506, 2021). "Both CTSD and CA9 are the important targets that have reported the therapeutic effects on breast cancer." (PMID 32420359, 2020). "In line with previous data, the relevance of co-operation between the intracellular domain of Notch-3 (NICD) and HIF-1α for CA9 expression (at the level of mRNA, protein, and reporter) was described in breast cancer cells." (PMID 32707920, 2020). "CA9 expression serves as a prognostic factor of patients with the cancers as follows: lung cancer, breast cancer, nasopharyngeal cancer, esophageal cancer, brain tumors, cervical carcinoma, and gastric cancer." (PMID 30863491, 2019).
breast carcinoma (continued). "In a clinical series of breast cancer patients, resistance to endocrine therapy combined with chemotherapy has been associated with overexpression of the HIF-1 alpha and CA9 proteins." (PMID 28430808, 2017). "CA9 expression was reported to be associated with HIF-1α, Notch3, VHL and multiple genes in renal cell carcinoma and/or breast carcinoma." (PMID 26156831, 2015). "A recent study reported that CA9 plays an important role in the expression of epithelial-mesenchymal transition in breast cancer and is a critical mediator of the expansion of breast cancer stem cells." (PMID 26156831, 2015). "Previously, we reported differential expression patterns of glycolysis-associated enzymes, including Glut-1, CA9, and monocarboxylate transporter 4 (MCT4) in tissues derived from different breast cancer subtypes." (PMID 24979213, 2014). "CA9 expression in resected tissue is prognostic of DFS in patients with resectable early-stage breast cancer treated by sequential FEC and weekly paclitaxel prior to resection." (PMID 24893880, 2014). "Overexpression of CA9 has been reported in a wide variety of malignant cell lines and tumors, including breast carcinomas, bladder cancer, and lung cancers." (PMID 23671581, 2013). "We then observed that in MCF7 cells, as well as in T-MS, hypoxia increased the mRNA expression of two crucial breast cancer stem cell regulatory genes, namely carbonic anhydrase 9 (CA9) and SNAI2, via de novo mRNA production." (PMID 24260469, 2013). "Here we analyzed the role of beta-catenin in the mRNAs production and stabilization of two important breast cancer stem cell regulatory genes, i.e. carbonic anhydrase 9 (CA9) and SNAI2." (PMID 24260469, 2013). "CA9 expression was correlated with Treg numbers in 448 breast cancers: increased numbers of Treg were observed in CA9 positive tumours (median Treg = 32, n = 66) compared to CA9 negative tumours (median Treg = 10, n = 382) (Mann-Whitney U P < 0.001)." (PMID 21521526, 2011). "Expression of CA9 has been reported in 48% of breast cancers, 79% of cervical cancers and 81% of lung cancers." (PMID 18841153, 2008). "In a study in breast cancer, peri-necrotic HIF-1α was associated with the expression of CA9 and Glut-1 and a poor prognosis." (PMID 17179985, 2007). "Tissue sections of the primary tumour and a lymph node metastasis of 60 patients with breast cancer were immunohistochemically stained for the hypoxia-markers carbonic anhydrase 9 (CA9), hypoxia-inducible factor-1α (Hif-1α) and DEC-1 and for CD34/Ki-67." (PMID 16251878, 2005). "Here, we set out to assess CA9 expression levels by real-time quantitative RT–PCR in breast cancer tissue samples obtained from 253 patients, and correlated those with relapse-free (RFS) survival." (PMID 12865916, 2003). "In the current study, CA9 is shown to be an independent predictor of RFS after adjuvant treatment in invasive resectable breast cancer patients, also when corrected for other clinicopathological factors." (PMID 12865916, 2003). "Thereby, we aimed at identifying a potential predictive value of CA9 for treatment success in breast cancer." (PMID 12865916, 2003). "PSAT1, CA6 and CA9 are part of the Metabolic Pathways and affect the growth and migration of breast cancer cells MIR100 and MIR124-2 are two MicroRNAs within the same signaling pathway that induce apoptosis and cell cycle arrest in breast cancer cells through multiple genes." (PMID 38254021, 2024). "In the realm of breast cancer, CA9 has been identified as an mRNA biomarker." (PMID 38338932, 2024). "Similarly, inverse correlation of CA9 with an immune activity signature was described for melanoma and basal-like breast cancer patients." (PMID 32707920, 2020). "Here we investigated the biological effects of CA9-silencing in breast cancer cell lines." (PMID 32560271, 2020).
breast carcinoma (continued). "We found that breast carcinoma cells that prefer bone as a metastatic site have very high extracellular proton efflux and expression of pumps/ion transporters associated with acid-base balance (MCT4, CA9, and V-ATPase)." (PMID 28903357, 2017). "Interestingly, pharmacological inhibition of CA9 catalytic activity leads to decreased overall tumor growth and reduction of the CICs population in a breast cancer cell line-derived xenograft model." (PMID 27901496, 2017). "An extensive hypoxic microenvironment as determined by CA9 expression in breast cancer might play a significant role in the resistance to chemotherapy." (PMID 24893880, 2014). "Moreover, CA9 has also been suggested as a predictive marker for response to doxorubicin treatment and adjuvant endocrine therapy in patients with breast cancer." (PMID 25128202, 2014). "CA9 expression in CNB specimens is a useful marker for predicting chemosensitivity, and CA9 expression in resected tissue is prognostic of DFS in patients with resectable early-stage breast cancer treated by sequential FEC and weekly paclitaxel prior to resection." (PMID 24893880, 2014). "Breast cancer cells under hypoxic conditions might be associated with aggressive tumor phenotypes, which may indicate a poor prognosis for patients with CA9-positive breast cancer, as suggested in previous studies." (PMID 24893880, 2014). "Hypoxic microenvironment as determined by CA9 expression in breast cancer might play a significant role in the resistance to chemotherapy, which indicates that CA9 expression in CNB specimens is a useful marker for predicting chemosensitivity to NAC." (PMID 24893880, 2014). "The basal-like/triple-negative breast cancer is a poorly differentiated and aggressive breast cancer subtype, characterized by the expression of a stem cell-like gene profile, by the cytoplasmic localization of beta-catenin and by CA9 and SNAI2 gene overexpression." (PMID 24260469, 2013). "CA9 had the strongest signal in the DU4475 breast cancer and AsPC-1 pancreatic cancer cell lines." (PMID 22087255, 2011). "Using CA9 as a surrogate marker of hypoxia, we demonstrated that hypoxia is associated with the accumulation of Treg and also the subset of CXCR4 positive Treg in breast cancer." (PMID 21521526, 2011). "In vitro studies have indicated that CA9 plays a role in the growth and survival of breast carcinoma cells; but its precise function in normal and cancerous tissues remains unclear." (PMID 18841153, 2008). "In a study of cutaneous breast cancer deposits, an infiltrative growth pattern, in which cancer cells respect the dermal architecture and co-opt pre-existing blood vessels, was characterised by CA9 expression in only 17% of the tumours." (PMID 15054467, 2004). "Thus, CA9 expression after NAC may be a clinically informative prognostic marker for breast cancer patients treated with NAC." (PMID 24893880, 2014). "Based on proteomic data from human biopsies, we additionally confirm the expression of cytosolic (CA1, CA2, CA3, CA13), mitochondrial (CA5β), and extracellular (CA4, CA6, CA9, CA12) carbonic anhydrases in breast cancer tissue." (PMID 37098526, 2023). "Most markedly CA9/Car9 and CA12/Car12 are upregulated, whereas CA4/Car4 is downregulated in human as well as murine breast cancer tissue." (PMID 37098526, 2023). "Histological analysis of breast cancer tissue specimens showed that 90% of necrotic-cancer regions express at least one standard indicator of hypoxia, such as HIF-1, CA9, or GLUT168." (PMID 35177645, 2022). "In human breast carcinoma, immunohistochemical studies have shown that fibrosis localized to hypoxic regions correlates with the expression of HIF-1 target gene carbonic anhydrase 9 (CA9)." (PMID 35884382, 2022). "We found that renal carcinoma cell lines expressed CA9, V1B2, V0C, and V1G1 subunits of V-ATPase that were confirmed also in breast carcinoma cell lines." (PMID 34124067, 2021).
breast carcinoma (continued). "Specifically, CA9 is a prognostic factor, hypoxic indicator, and promising therapeutic target, as inhibiting CA9 can enhance anti-PD-1 and anti-CTLA-4 blockade in melanoma and breast cancer models." (PMID 33808542, 2021). "The mRNA levels of EPAS1 as well as TGFB1, VEGFA and CA9, were confirmed to be positively correlated with those of SIPA1 in these two pairs of breast cancer cells and BT549, another TNBC cell line." (PMID 35096814, 2021). "The results showed that cyanidin 3-[2-(glucosyl)-6-(sinapoyl)glucoside]-5-glucoside was successfully docked into the breast cancer-related proteins, CTSD and CA9." (PMID 32420359, 2020). "Real-time PCR verified the increased expression of CA9 and decreased expression of BIRC3 and ACSL4 in the breast cancer cell line." (PMID 27478411, 2016). "Expression of the CA9 protein and the BRCA1 (breast cancer 1) protein are inversely correlated in patients with breast cancer." (PMID 27478411, 2016). "The current study detected increased expression of CA9 in the anti-PADI2 siRNA-treated breast cancer cell lines, supporting the importance of the PADI2-CA9 pathway in breast cancer progression." (PMID 27478411, 2016). "The aim of this study was thus to clarify the correlation between expression of the hypoxic marker carbonic anhydrase-9 (CA9) and chemosensitivity to NAC as well as prognosis of breast cancer patients." (PMID 24893880, 2014). "In this retrospective study, we examined the correlation between CA9 expression and chemosensitivity to NAC in breast cancer as well as the prognosis of patients." (PMID 24893880, 2014). "We then investigated the role of beta-catenin in the regulation of the CA9 and SNAI2-dependent breast cancer stem cell phenotype." (PMID 24260469, 2013). "The expression of NCCRP1 and CA9 was measured by QRT-PCR in 16 pancreatic cancer cell lines and 21 breast cancer cell lines." (PMID 22087255, 2011). "We, therefore, investigated CXCR4 expression in Treg, together with the expression of CA9 and CXCL12 in basal-like and other subtypes of breast cancers." (PMID 21521526, 2011). "Previous breast cancer studies showed that in hypoxic conditions, HIF-1α expression is seen perinecrotically, with induction of its target genes carbonic anhydrase 9 (CAIX), that plays a role in pH regulation and Glut-1, a transmembrane glucose transporter." (PMID 20565904, 2010). "In addition, Dysadherin KD by shRNA decreased CA9 expression in SK-Hep-1 liver cancer cells and MDA-MB-231 breast cancer cells." (PMID 41535258, 2026). "So, both CA9 and FOXM1 were novel markers of poor prognosis for breast cancer patients." (PMID 38561760, 2024). "Whereas CA9 and CA12 are prognostic markers and proposed pharmacological targets in breast cancer, the consequences of these and other carbonic anhydrases in specific breast cancer molecular subtypes remain unclear." (PMID 37098526, 2023). "In contrast, CA9 drives most of the negative survival effect of extracellular carbonic anhydrases in Basal-like breast cancer (HR = 1.313)." (PMID 37098526, 2023). "For example, carbonic anhydrase IX (CA9) is used in breast cancer but as it is not expressed in all tumor types would not represent a general biomarker." (PMID 36057753, 2022). "In 2D hypoxia, the expression of CA9 was present in all breast cancer cells exposed to hypoxia and absent in cells grown in normoxic culture conditions, confirming a hypoxic response." (PMID 35841287, 2022). "Moreover, HIF-1-induced carbonic anhydrase 9 (CA9) expression is a requisite for the mobilization of granulocytic MDSCs, driven by the granulocyte-colony stimulating factor (G-CSF), to the breast cancer lung PMN." (PMID 35006432, 2021). "Supuran and colleagues found that selective CA9 inhibitors inhibited cell migration and spreading of breast cancer cells in the absence of oxygen, suggesting that CA9 is a pivotal target for antitumor therapy in patients with breast carcinoma." (PMID 24893880, 2014).